IL34 (interleukin 34)
Diseases named in the same sentence as IL34 in open-access papers (continued):
Sharing a sentence is not in itself a finding about the gene and the disease.
hepatocellular carcinoma (19 papers, 2017 to 2024). A malignant tumor that arises from hepatocytes. "Zhou SL and colleagues showed miR‐28‐5p deficiency in hepatocellular carcinoma was closely associated to cancer metastasis by inducing IL‐34 overexpression and increased TAM infiltration." (PMID 35132816, 2022). "In this study, we investigated the expression, biological function and associated mechanisms of IL‐34 in HBV‐related hepatoma cells." (PMID 31621133, 2019). "In such a neoplasia, as well as in other tumors (i.e. teratoma, hepatocellular carcinoma), the pro-tumoral effect of IL-34 would be linked to the ability of the cytokine to promote the survival and the differentiation of type 2 macrophages." (PMID 29423057, 2018). "In addition, we transfected hepatoma cells with HBV plasmids or HBV plasmids with HBX mutation to further detect the effect of HBX on IL‐34 expression in HCC cells with HBV infection." (PMID 31621133, 2019). "According to Shao-Lai Z., IL-34, produced by hepatocellular carcinoma (HCC) cells, induced the recruitment of TAMs at tumor sites." (PMID 38254773, 2024). "This is consistent with others, showing that HBx gene of HBV (part of HBV DNA) upregulates IL-34 expression in hepatoma." (PMID 35347503, 2023). "Other research has reported that in hepatoma cells, HBx increases IL-34 expression in a transcription factor CCAAT/enhancer-binding protein α (CEBP/α)-dependent way." (PMID 34456908, 2021). "In hepatocellular carcinoma, IL‐34 exerts its effect by stimulating the differentiation of tumor‐associated macrophages (TAM), leading to tumor metastasis." (PMID 32573824, 2020). "Dependent on HBX, HBV increased IL‐34 expression in hepatoma cells, and HBX upregulated and interacted with CEBP/α to enhance the activity of IL‐34 promoters." (PMID 31621133, 2019). "When HBX‐positive cells were treated with IL‐34 shRNA, the proliferation of hepatoma cells mediated by HBX was declined." (PMID 31621133, 2019). "We also explore the expression of IL‐34 in hepatoma cells stably transfected with HBX or control plasmids." (PMID 31621133, 2019). "Via CSF1‐R and CD138, IL‐34 promoted the proliferation and migration of hepatoma cells, and contributed to the activation of ERK and STAT3 pathways and the upregulation of Bcl‐xl and c‐Myc mediated by HBX." (PMID 31621133, 2019). "When HBX‐positive cells were treated with IL‐34 shRNA or IL‐34 neutralizing antibody, the migration of hepatoma cells mediated by HBX was inhibited." (PMID 31621133, 2019). "We explored if combination of IL-34 and APF could improve the diagnostic value in HBV related hepatocellular carcinoma (HBV-HCC)." (PMID 35347503, 2023). "Moreover, IL‐34 expression was highly increased in patients with hepatocellular carcinoma and was correlated with poor prognosis and survival rates." (PMID 32573824, 2020). "We further determine the effect of IL‐34 on the development of hepatoma cells in vivo." (PMID 31621133, 2019). "Next, HBV and control plasmids were transfected into HepG2 and Huh7 cells, and we found that HBV could increase IL‐34 expression in both two types of hepatoma cells." (PMID 31621133, 2019). "Taken together, these results suggest that HBX could bind to the promoter region of IL‐34 via the interaction with CEBP/α in hepatoma cells." (PMID 31621133, 2019). "Interleukin‐34 (IL‐34) is associated with hepatitis B virus (HBV) infection and hepatocellular carcinoma (HCC)." (PMID 31621133, 2019). "Furthermore, both IL-34 protein and mRNA levels were declined hepatoma cells expressing HBV." (PMID 28614380, 2017). "In addition, it has been reported that IL-34, produced by hepatocellular carcinoma (HCC) cells, recruits TAMs to tumor sites, and correlates with metastasis and poor prognosis in HCC." (PMID 39457693, 2024). "Together, these results suggested that IL‐34 contributed to the activation of ERK and STAT3 signal pathways mediated by HBX in hepatoma cells." (PMID 31621133, 2019).
hepatocellular carcinoma (continued). "In hepatocellular carcinoma (HCC), neoplastic cell-derived IL-34 stimulates TAMs to produce TGF-β1." (PMID 31968663, 2020). "Furthermore, our results showed that PI3‐K and NF‐κB pathways were responsible for IL‐34 expression mediated by HBX, and the increase of IL‐34 induced by PI3‐K and NF‐κB pathways was dependent on CEBP/α in hepatoma cells." (PMID 31621133, 2019). "We measured the expression of IL‐34 mediated by the virus, and the results showed that HBV could increase IL‐34 expression in hepatoma cells." (PMID 31621133, 2019). "IL‐34 expression induced by HBV and HBV X (HBX) gene was measured in hepatoma cells." (PMID 31621133, 2019).
liver fibrosis (15 papers, 2016 to 2025). "Of particular interest is the fact that IL-34 is closely associated with the active phase of hepatitis and has been found to be an essential indicator of a prediction model of liver fibrosis." (PMID 38890719, 2024). "In conclusion, the IL-34 based fibrosis score, including serum IL-34, type IV collagen 7s and age, is a feasible diagnostic marker of liver fibrosis in NAFLD patients." (PMID 27363523, 2016). "Additionally, circulating IL-34 has been associated with inflammatory activity and liver fibrosis in chronic hepatitis B (CHB) patients." (PMID 35347503, 2023). "This inhibits TNF-α blocking the IL-34-associated liver fibrosis." (PMID 33408768, 2021). "In addition, IL-34 shows promise as a diagnostic marker for diverse inflammatory conditions, including liver fibrosis, atherosclerosis, Hashimoto’s thyroiditis, and lupus nephritis." (PMID 32801364, 2020). "A novel diagnostic marker IL34-FS, which includes the factors of serum IL-34, type IV collagen 7s and age, could be feasible for the diagnosis of liver fibrosis in patients with NAFLD." (PMID 27363523, 2016). "IL-34 may also be associated with inflammatory activity and liver fibrosis in CHB." (PMID 35347503, 2023). "Therefore, further investigation is needed to decide whether IL-34 is a feasible marker of liver fibrosis caused by other etiologies, such as viral hepatitis or autoimmunity." (PMID 27363523, 2016). "In this study, Mfs induced with IL-34-based conditions were shown to be effective in the treatment of liver fibrosis in mouse models." (PMID 39856797, 2025). "In both acute and chronic liver damage experiments, interleukin 34-induced macrophages significantly ameliorated liver fibrosis." (PMID 39856797, 2025). "It is therefore likely that human IL-34 + IL-4-induced Mfs are as effective against liver fibrosis as in mice." (PMID 39856797, 2025). "In this study, we clearly indicated that IL-34-induced Mf, particularly when alternatively activated by the addition of IL-4, significantly ameliorated liver fibrosis in mouse models." (PMID 39856797, 2025). "The results indicate that Mf induced by IL-34-based conditions has a substantial capacity to ameliorate liver fibrosis." (PMID 39856797, 2025). "We then focused on the effect of IL-34 + IL-4 Mf in the formation of hepatic fibrosis in the TAA model." (PMID 39856797, 2025). "The primary aim of this study was to investigate the effects of Mf induced by IL-34-based conditions on liver fibrosis." (PMID 39856797, 2025). "In this experiment, IL-34 + IL-4-induced Mf showed the strongest potential to treat liver fibrosis among the Mfs examined." (PMID 39856797, 2025). "This study suggests an alternative IL-34-using protocol to generate autologous Mf for the treatment of liver fibrosis." (PMID 39856797, 2025). "Interleukin 34-induced macrophages, particularly when additionally stimulated with interleukin 4, significantly ameliorated the liver fibrosis." (PMID 39856797, 2025). "In contrast, the IL-34 + IL-4 Mfs significantly suppressed liver fibrosis compared to the saline or IL-34 alone group." (PMID 39856797, 2025). "In a concanavalin A (ConA)-induced AIH mouse model, splenectomy and IL-34 were found to drive M2 polarization which suppressed hepatic fibrosis and inflammation." (PMID 37818371, 2023). "The serum level of IL-34 is related to inflammatory activity in the liver and is highly sensitive to severe liver fibrosis in patients with chronic hepatitis B virus infection." (PMID 32801364, 2020). "Noninvasive biomarkers of liver fibrosis, such as IL-34 identified by us, is of clinical importance for the follow-up of patients who attained SVR." (PMID 29201774, 2017). "Here we propose a predictive model of liver fibrosis based on IL34-FS consisting of serum IL-34, type IV collagen 7s and age, by multiple regression analyses." (PMID 27363523, 2016).
liver fibrosis (continued). "Using IL34-FS, we were able to estimate liver fibrosis in patients with NAFLD from significant fibrosis to liver cirrhosis." (PMID 27363523, 2016). "In this study, we identified serum IL-34 as a marker of liver fibrosis by comprehensive analysis of cytokines, chemokines, and hematopoietic factors." (PMID 27363523, 2016). "IL-34 based fibrosis score (0.0387*IL-34 (pg/ml) + 0.3623*type IV collagen 7s (ng/ml) + 0.0184*age (year)–1.1850) was a practical predictive model of liver fibrosis." (PMID 27363523, 2016). "In univariate analyses, IL-34, M-CSF, sCD163, hyaluronic acid, type IV collagen 7s, APRI, FIB-4 index, and NFS were associated with liver fibrosis in each stage." (PMID 27363523, 2016). "In summary, we showed that IL-34 can serve as an independent marker of liver fibrosis in NAFLD patients, the expression of which is mainly on liver fibroblasts." (PMID 27363523, 2016). "Similarly, we induced Mfs from mouse bone marrow cells using IL-34 and administered them to mice with CCl4-induced liver fibrosis." (PMID 39856797, 2025). "Next, we investigated whether treatment with the alternatively activated Mf induced by IL-34 + IL-4 was also effective in liver fibrosis models." (PMID 39856797, 2025). "Liver fibrosis was significantly inhibited with the IL-34 + IL-4 Mf treatment." (PMID 39856797, 2025). "In this study, we investigated the capacity of IL-34 Mf to improve liver fibrosis." (PMID 39856797, 2025). "Finally, we examined the therapeutic effect of human IL-34 + IL-4 Mf in a liver fibrosis model using immunodeficient NSG mice in which human PBMCs had been administered (see the Methods section)." (PMID 39856797, 2025). "Furthermore, IL-34 has been demonstrated to play a crucial role in hepatitis C-related liver fibrosis." (PMID 40176879, 2025). "Therefore, it is possible that Stat6 similarly regulates the phenotype and function of IL-34 + IL-4 Mf in the treatment of liver fibrosis at the transcription factor level." (PMID 39856797, 2025). "Infection by hepatitis C virus (HCV) is associated with the formation of chronic liver diseases such as liver fibrosis, and IL-34 may contribute to this pathogenesis." (PMID 33408768, 2021). "As with HCV, hepatitis B virus (HBV) infections can lead to hepatic fibrosis and chronic inflammation in which IL-34 may be involved." (PMID 33408768, 2021). "We found that IL-34 increased with the progression of liver fibrosis and that IL-34 could serve as an independent marker of liver fibrosis." (PMID 27363523, 2016). "IL-34 increased with the progression of fibrosis and was an independent marker for liver fibrosis." (PMID 27363523, 2016). "We showed that IL-34 was increased in sera of HCV patients with advanced liver fibrosis." (PMID 27363523, 2016). "Thus, the administration of IL-34 Mf has potential in the treatment of liver fibrosis." (PMID 39856797, 2025). "Therefore, mechanisms of liver fibrosis inhibition by IL-34 + IL-4 Mf may function in a complex manner at multiple points." (PMID 39856797, 2025). "Besides suppressing hepatic stellate cells, IL-34 + IL-4 Mfs significantly suppressed liver parenchymal cell damage and T cell activation, which is upstream of the liver fibrosis process." (PMID 39856797, 2025). "Interestingly, a novel non-invasive diagnostic index termed “IL34-FS”, which includes the variables serum IL-34, type IV collagen 7s and age, was introduced for the diagnosis of hepatic fibrosis in patients with NAFLD; however, this index requires external validation." (PMID 40794228, 2025). "However, because the size of HCV cohort was small, we were not able to confirm the validity of IL-34 as a diagnostic marker for liver fibrosis in HCV patients." (PMID 27363523, 2016). "TGF-β1 is the most potent fibrogenic cytokine for HSC activation, and the regulatory roles ofS. japonicum-derived molecules on hepatic fibrosis mainly target the TGF-β1, interleukin-34 (IL-34), and HSCs." (PMID 39314046, 2024).
liver fibrosis (continued). "IL-34 promotes M2 macrophage polarization and inhibits NK cell killing of HSCs to promote liver fibrosis; however, SEA inhibits IL-34 expression." (PMID 36389166, 2022). "From these data, we aimed to investigate the possibility of IL-34, M-CSF, sCD163, MIP-3α/CCL20, hyaluronic acid, type IV collagen 7s, APRI, FIB-4 index, and NFS as a marker of liver fibrosis in NAFLD patients." (PMID 27363523, 2016). "The therapeutic capacity of IL-34 Mf for liver fibrosis seems consistent to, or at least not inferior to, that of CSF-1 Mf." (PMID 39856797, 2025). "Interestingly, the level of IL-34 detected in blood plasma differed according to the phases of chronic HBV infection and correlated with progression of liver fibrosis and poor prognosis." (PMID 33408768, 2021). "However, the therapeutic capacity for liver fibrosis by interleukin 34-induced macrophages has not been evaluated." (PMID 39856797, 2025).
osteosarcoma (14 papers, 2018 to 2025). A usually aggressive malignant bone-forming mesenchymal neoplasm, predominantly affecting adolescents and young adults. "M2-like TAMs induced resistance to chemotherapy in primary osteosarcoma cells, by releasing IL-1β, which in response caused the overexpression of IL-34, vasculogenesis, and osteosarcoma growth." (PMID 37958467, 2023). "IL-34 expression has been observed in giant cell tumors of bone and human osteosarcoma cell lines and is associated with the progression of neoplasia." (PMID 33800170, 2021). "Elevated levels of IL-34 were also documented in cell lines of human osteosarcoma and were associated with disease progression." (PMID 34535634, 2021). "The contribution of IL-34 to osteoclastogenesis, bone-associated inflammatory diseases, and osteosarcoma cell proliferation suggests that IL-34 acts as a pathogenic molecule in bone disease." (PMID 33408768, 2021). "IL-34 is associated with the progression of osteosarcoma and an increase in neo-angiogenesis." (PMID 39252946, 2024). "For instance, IL-34 expression was seen in giant cell tumors of bone human osteosarcoma and human osteosarcoma cell lines, and it is associated with the progression of the neoplasia (that is, increased tumor growth and lung metastases), as well as with an increase of neo-angiogenesis." (PMID 31968663, 2020). "In osteosarcoma, it has been observed that IL-34 can promote M2 macrophage polarization of osteosarcoma TAMs and induce angiogenesis." (PMID 39359731, 2024). "On the other hand, IL-34 induces the adhesion of monocytes to endothelial cells, improving the migration capacity of TAMs, which was observed in osteosarcoma." (PMID 37958467, 2023). "The cytokines VEGF, IL-17, IL-6, IL-8, IL-1Ra, TNF-α, and IL-34 can promote the proliferation of osteosarcoma cells, and TGF-β exerts dual effects on tumors; they inhibit tumor growth in the early stage and promote tumor growth in the late stage." (PMID 35102149, 2022). "Among these, VEGF, IL-17, IL-6, IL-8, IL-1Ra, TNF-α, and IL-34 can promote cell proliferation in osteosarcoma; only TGF-β has a dual role in the tumor." (PMID 35102149, 2022). "In osteosarcoma, IL-34 has been shown to promote tumor progression and metastasis by recruiting tumor-associated macrophages (TAMs)." (PMID 33800170, 2021). "For instance, IL-34 facilitated macrophage extravasation and polarization toward the M2 phenotype and promoted osteosarcoma proliferation and metastasis expansion." (PMID 33408768, 2021). "IL-34 then appeared as a pro-proliferative and metastatic factor in osteosarcoma, with a potential role in angiogenesis via glycosaminoglycan." (PMID 33408768, 2021). "Osteosarcoma cell lines with overexpression of CSF-1R ligands CSF-1 and IL-34 have a propensity to polarize TAMs to the M2 subtype, resulting in more progressive disease in a murine osteosarcoma model." (PMID 32961800, 2020). "IL-34 was released by osteosarcoma cells and promoted the recruitment of M2-TAMs into the tumor tissue, thus promote tumor growth and metastasis." (PMID 33363016, 2020). "IL-34 promotes tumor progression and metastatic processes in osteosarcoma via the induction of angiogenesis." (PMID 29472590, 2018). "Notably, it has been found that TAMs were recruited by interleukin-34 (IL-34) released from osteosarcoma cells and infiltrated massively into osteosarcoma tissues." (PMID 33363016, 2020). "M2 could be recruited by IL34 and promote osteosarcoma growth." (PMID 36814925, 2023). "Previous reports have shown that the cytokines VEGF, IL-17, IL-6, IL-8, IL-1Ra, TNF-α, IL-34, and TGF-β play a role in the development of osteosarcoma." (PMID 35102149, 2022). "For instance, pro-inflammatory cytokines, such as TNF-α and IL-1β, enhance IL-34 synthesis in fibroblasts, epithelial cells, intestinal lamina propria mononuclear cells (LPMC), periodontal ligament cells, osteosarcoma cells, and adipocytes, through NF-κB- and MAP kinase-dependent pathways." (PMID 31968663, 2020).